WNT10B (Wnt family member 10B)
Diseases named in the same sentence as WNT10B in open-access papers (continued):
Sharing a sentence is not in itself a finding about the gene and the disease.
T-cell acute lymphoblastic leukemia (1 paper, 2023). Acute lymphoblastic leukemia of T-cell origin. "WNT10B also interacted with FZD6 in a T-cell acute lymphoblastic leukemia cell line and HEK293T cells, as demonstrated by immunoprecipitation and PLA." (PMID 36814601, 2023). "Specifically in acute myeloid leukemia (AML), WNT10B signals through FZD4 and FZD5, while in T-cell acute lymphoblastic leukemia, WNT10B signals through FZD6." (PMID 36814601, 2023).
thyroid cancer (1 paper, 2023). "shRNA (small hairpin RNAs) knockdown of HOTAIRM1 markedly increased expression of miR-148a and decreased expression of WNT10B in thyroid cancer cell lines (TPC-1 and BCPAP)." (PMID 36814601, 2023). "Using the TargetScan database and luciferase assays, they demonstrated that miR-148a directly binds to and suppresses WNT10B at the 3′-UTR in thyroid cancer cells." (PMID 36814601, 2023). "Overall, HOTAIRM1 inhibits miR-148a, which allows for aberrant expression of WNT10B in thyroid cancer." (PMID 36814601, 2023).
type 2 diabetes (1 paper, 2018). "Variants of the TCF7/2 gene are linked to increased susceptibility for type 2 diabetes, while a SNP in the human WNT10b gene has been associated with early-onset familial obesity." (PMID 29514067, 2018).
tumor (43 papers, 2012 to 2026). "The loss of tumor growth coincided with the loss of WNT10B, β-catenin, and canonical WNT target genes (MYC, JUN, CD44, and MET) in BCSCs." (PMID 36814601, 2023). "In conclusion, the TAZ/WNT10B axis (ferroptosis-related pathway) is regarded as a tumor immune-related regulatory pathway via integrated bioinformatics analysis." (PMID 34367965, 2021). "Combined with correlation and survival analyses, the TAZ/WNT10B axis was identified as a tumor immune-related regulatory pathway." (PMID 34367965, 2021). "The protein levels of Wnt10B and β‐catenin in tumor tissues were reduced by miR‐107 mimic or sh‐E2F1." (PMID 34758200, 2021). "Functional rescue assays showed that overexpression of WNT10B reversed the tumour-suppressive roles of KB-68A7.1, whereas the oncogenic roles of KB-68A7.1 depletion were abolished by Wnt/β-catenin signalling inhibitor." (PMID 35127520, 2021). "Several Wnt genes were induced by MAPKi treatment in BPN tumor cells, including Wnt2b, Wnt4, Wnt8b, and Wnt10b." (PMID 33821796, 2021). "For example, DNA aptamer-decorated extracellular vesicles loaded with Cas9 RNPs achieved tumor-specific targeting and WNT10B knock-out in human primary liver cancer-derived organoids and xenograft tumor models, and subsequent tumor growth inhibition in vivo." (PMID 33027946, 2020). "HMGA2 mediates the proliferative response of tumor cells to WNT/-CATENIN signaling pathway in a Wnt10b-driven breast cancer model." (PMID 31963852, 2020). "The response to WNT10B is abolished by interfering with HMGA2 function in Wnt10b-driven tumor cells." (PMID 31963852, 2020). "We first performed immunohistochemical staining and Western blot analysis to determine Wnt10b expression in HCC and adjacent normal tissues, and showed that Wnt10b was significantly overexpressed in HCC tumor tissue." (PMID 31727171, 2019). "The expression levels of Wnt2B, Wnt3A, Wnt6, Wnt8B and Wnt10B were significantly higher in primary liver tumor tissues than which in adjacent non-tumor tissues." (PMID 30814912, 2019). "Silencing of FHL2, a β-catenin interacting protein, reduced WNT signaling in OS cells, the expression of WNT5A and WNT10B and tumor formation and lung metastasis in a mouse OS model." (PMID 25992885, 2015). "Using parental SUNE1 cells as controls, the PCR assays showed the increased expression of β-catenin and Wnt10B in all tumor samples, including both control and Wnt-C59-treated mice." (PMID 25980501, 2015). "In sequential tumour sections the expression of WNT10B and β-CATENIN correlate in similar regions (i.e. arrow and arrow-heads)." (PMID 23307470, 2013). "In the present study, we provide evidence that Wnt10b-driven tumours are devoid of ERα, PR and HER2 protein expression and can be used as a translational model for human TNBC." (PMID 23307470, 2013). "We have recently shown that mechanistically Wnt10b-driven (Wnt10bTG) tumours degrade the tumour suppressor p27Kip1 in a SKP2-independent manner mediated by CUL4A E3-ligase activity leading to increased proliferation." (PMID 23307470, 2013). "These cell proliferation markers (amongst others) are also upregulated in Wnt10b-driven tumours, as shown by microarray gene expression analysis and verifying qt-PCR." (PMID 23307470, 2013). "In all, 4/16 of the neoplasia expressed Fgf3, 7/16 expressed Wnt-1, 6/16 expressed Wnt10b, and 11/16 expressed Rspo2." (PMID 23866257, 2013). "In parallel, we also wanted to determine if mammosphere formation from primary tumour cells would be dependent on Wnt10b-secretion and therefore treated the cells with Wnt-C59." (PMID 23307470, 2013). "Next we illustrate that in our cohort of TNBC samples HMGA2, like WNT10B, has predictive value for tumour size >1.5 cm (n = 45, τ = 0.33, p = 0.007) and high nuclear grade status 3 (n = 26, τ = 0.37, p = 0.047)." (PMID 23307470, 2013). "Wnt10b-driven tumours, when compared to ErbB2TG-driven tumours, have an increased expression pattern for G1-, S- and G2-phase Cyclins." (PMID 23307470, 2013).
tumor (continued). "We provide evidence that transgenic murine Wnt10b-driven tumours are devoid of ERα, PR and HER2 expression and can model human TNBC." (PMID 23307470, 2013). "MMTV integration near the Wnt1/Wnt10b and Fgf3/Fgf4 loci can lead to the expression in the same tumor of one or the other or both genes in these clusters." (PMID 23131872, 2012). "Additionally, the miR-148a/WNT10b axis inhibits tumor growth and enhances sensitivity to cisplatin when the expression levels of LINC00261 are elevated through its interaction with WNT10b (wingless-type MMTV integration site family, member 10B)." (PMID 40136629, 2025). "Finally, using a xenograft nude mouse model we demonstrated that knockout of NSD1 suppresses the expression of Wnt10b, thus inhibiting the proliferation and migration of tumor cells in vivo by inactivating the Wnt/β-catenin signaling pathway." (PMID 31727171, 2019). "Compelling evidence indicates that Wnt10B may be a valuable therapeutic target for TNBC, and a transgenic murine model with a Wnt10B-driven tumor is shown to have characteristics of human TNBC." (PMID 29069872, 2017). "Based on the preceding experiments, we hypothesized that one potential function of HMGA2 in Wnt10b-driven tumours is the control of proliferation." (PMID 23307470, 2013). "In this study we have identified HMGA2 as the most highly expressed gene in Wnt10b-driven tumours." (PMID 23307470, 2013). "Wnt10b-driven tumours are phenotypically like human TNBC—devoid of ERα, PR and HER2." (PMID 23307470, 2013). "Furthermore, Wnt10b-driven tumours express the basal-epithelial markers CK5 and CK6, in contrast to ErbB2TG tumours." (PMID 23307470, 2013). "We next revisited our previously defined ‘intrinsic proliferation signature’ from our Wnt10b-driven tumours and hypothesized that a translational TNBC model should preserve this signature in human TNBC cells." (PMID 23307470, 2013). "In BCa organoids, activation of the Wnt/β-catenin pathway was restricted to tumor cells in the RT-112, T-24 and CAL-29 organoids, which showed significantly enhanced cytoplasmic and nuclear β-catenin after only 5 to 10 min of Wnt10B." (PMID 38001959, 2023). "In vivo, WNT10B knockdown and NSD1 knockout were sufficient to reduce tumor volume and weight, and the combination knockdown/knockout further suppressed tumor volume and weight and reduced pulmonary metastasis significantly." (PMID 36814601, 2023). "To this end, we checked if there was differential expression of Wnt ligands including WNT1, WNT3 and WNT10B among normal liver and HCC tumor tissues." (PMID 35003366, 2021). "KB-68A7.1 functions as a tumour suppressor via binding to and sequestrating NSD1 in the cytoplasm, reducing WNT10B transcription, and repressing Wnt/β-catenin signalling." (PMID 35127520, 2021). "Collectively these results demonstrate that silencing Wnt10b in combination with NSD1 knockout imposes a significant blockade in the Wnt/β-catenin signaling pathway, and thereby strongly inhibits tumor formation as well as extent of metastatic lesions in vivo." (PMID 31727171, 2019). "Strikingly, silencing Wnt10b in combination with a knockout of NSD1, further suppressed the volume and weight of xenograft tumor in nude mice." (PMID 31727171, 2019). "We illustrate that WNT10B induces transcriptionally active β-catenin in human TNBC and predicts survival-outcome of patients with both TNBC and basal-like tumours." (PMID 23307470, 2013). "We confirmed the presence of active virus in Mtv-1/NIV infected tissues and using quantitative reverse transcription PCR (qRT-PCR) found that Mtv-1/NIV induced neoplasms (tumors and hyperplasia) commonly expressed the core CIS genes Wnt1, Wnt10b, Rspo2, Fgf3." (PMID 23866257, 2013). "We show that both WNT10B and HMGA2 are highly expressed in a subset of human primary TNBC tumours correlating with predictive poor survival outcome in both basal-like and TNBC patients." (PMID 23307470, 2013).
tumor (continued). "Results demonstrated an invariably unmethylated (WNT10B) or methylated (TUB, ALOX12B, SLC6A11) status of the normal samples (data not shown) as compared to the variable levels of methylation observed in tumor cells." (PMID 22950745, 2012). "They established that targeting the LINC00261-miRNA-148a/WNT10b axis could significantly affect CRC cell proliferation and apoptosis, highlighting its importance in tumor growth and programmed cell death." (PMID 40136629, 2025). "In addition to therapeutics and understanding more about WNT10B regulation in different cell types, emerging areas for WNT10B studies may include fetal growth restriction and placenta biology, immune-oncology, and the tumor microenvironment in various cancer types." (PMID 36814601, 2023). "Supporting the notion that WNT10B was responsible for the stabilization and activation of β-catenin and the increased aggressiveness of both 4T1 and MDA-MB-231 cells, silencing of WNT10B by short hairpin RNA in p85α−/− CAFs reversed invasion and tumor growth." (PMID 36814601, 2023). "These tumours also displayed high expression levels of epidermal differentiation genes (such as IVL, LOR and KRT1), indicating that these tumours had undergone squamous metaplasia, and an activation of the WNT/β-catenin signalling pathway (expression of WNT10B and LEF1)." (PMID 34916592, 2022). "However, we cannot preclude additional paracrine factors also contributing to tumor formation since transcripts for other secreted growth regulators (SOST, BMP7, BMP8A, WNT5B, WNT10B, and FGF21) exhibited increased abundance in SHP2-depleted pellet cultures." (PMID 24875294, 2014). "Interestingly, the Wnt10b tumorigenic mouse model contrasts the MMTV-Wnt1 model, in part, because Wnt1-driven tumours have been reported to express hormone receptors." (PMID 23307470, 2013). "Moreover, we analyzed the correlation among four-gene signature (FeSig) (BID, TAZ, MT1G, and SLC7A11), downstream hub genes (CPNE7, WNT10B, ADAMTS14, and RUFY4), and immune checkpoints (PD-1, CTLA4, LAG3, and TIGIT) to further discover potential molecular mechanisms of tumor immunity." (PMID 34367965, 2021). "We have shown that the WNT10B/β-catenin/HMGA2/EZH2 signaling axis is critically important in chemo-resistant TNBC and that targeting this network can prolong survival by repressing primary tumor growth and multi-organ metastases to both the lungs and lymph nodes." (PMID 31861131, 2019). "We checked for changes in expression of Wnt ligands, and although there was a trend toward significantly increased expression of Wnt2, Wnt5b, Wnt8b, and Wnt10b specifically in the tumor and not the neighboring normal tissue, the changes did not quite reach statistical significance (Fig EV2A and B)." (PMID 28183841, 2017). "It is worth noting that the expression of two additional genes tested but not shown, Wnt1 and Wnt10b, was detectable in the mouse tumor tissues, but was below the limit of detection in the controls; thus, while the relative analysis was not possible, these genes were also up‐regulated." (PMID 26778414, 2016). "Thus, Wnt10b signaling might act as a suppressor of CIN that is a well-established driving force for the generation of high genetic heterogeneity and variability in cancer supporting tumor evolution toward aggressive growth phenotypes, metastasis, and therapy resistance." (PMID 40846632, 2025). "Expression of WNT10B is absent or low in ER+, PR+ and HER2+ tumours." (PMID 23307470, 2013).
cancer (37 papers, 2011 to 2026). A tumor composed of atypical neoplastic, often pleomorphic cells that invade other tissues. "WNT10B promotes proliferation, invasion and other malignant functions and is associated with decreased survival in multiple cancer types." (PMID 36809527, 2023). "For example, exosomal Wnt10b from p85-deficient fibroblasts can promote cancer progression via epithelial-to-mesenchymal transition (EMT) induced by the canonical Wnt pathway." (PMID 33578954, 2021). "In summary, JA interferes with TNBC cell proliferation at differential IC50 values based on the cancer cell line etiology-subtype, the known cellular chemoresistance status and/or associations with elevated mRNA levels for WNT10B." (PMID 29281678, 2017). "Hence, we propose that Wnt10b signaling acts in cancer cells during S phase–associated replication stress as a rescue pathway to limit genome instability." (PMID 40846632, 2025). "Wnt10b has been implicated as a paracrine chemotactic factor in cancers." (PMID 33914869, 2021). "Very similarly, CIN+ cancer cells suffering from endogenous replication stress also exhibited increased microtubule dynamics in the S phase, which was rescued by Wnt10b addition." (PMID 40846632, 2025). "Epigenetic dysregulation of wnt/β-catenin signalling genes has been well characterized in cancers, examples ranging from promoter hypermethylation of WNT10B to histone modification-driven overexpression of WNT2." (PMID 41266313, 2025). "Together, these data indicate that Wnt10b signaling acts during the S phase to suppress mitotic errors induced by DNA replication stress in human cancer cells." (PMID 40846632, 2025). "The authors describe a novel role of Wnt10b signaling acting in response to DNA replication stress to suppress chromosomal breaks and mitotic errors in human cancer cells." (PMID 40846632, 2025). "Intriguingly, our work demonstrates that activation of Wnt10b signaling in cancer cells suffering from RS is sufficient to suppress both the generation of chromosomal breaks and the generation of mitotic errors." (PMID 40846632, 2025). "POSTN (periostin), known to be secreted from cancer-associated fibroblast (CAF), and wingless-type MMTV integration site family member 10B (WNT10B), which promote EMT, were also found to be inhibited by the PT complex." (PMID 38027033, 2023). "Cancer-associated fibroblasts (CAFs) isolated from OSCC tumors have significantly decreased expression of miR-148a and significant overexpression of WNT10B by qPCR compared to normal fibroblasts." (PMID 36814601, 2023). "WNT ligands regulate stem cell biology, and WNT10B has been ascribed roles in mesenchymal, mammary, prostate, skin, hematopoietic, dental pulp, and cancer stem cells." (PMID 36814601, 2023). "An up-regulation of the components of WNT/β-catenin, in particular of WNT10a and WNT10b, along with change in the expression pattern of β-catenin has been documented in cancer patients." (PMID 37628609, 2023). "As a significant member of the Wnt family, Wnt10b can activate the Wnt/β-catenin signalling pathway and contribute to the biological functions of cancer cells." (PMID 32913459, 2020). "Wnt10b is considered a potential oncogene in human cancer that interacts with other Wnt family members to promote the Wnt/β-catenin signalling pathway 24-25." (PMID 32913459, 2020). "Investigation of miR-148a function demonstrated that overexpression of miR-148a in CAFs significantly impaired the migration and invasion of cancer cells by directly targeting WNT10B." (PMID 29347950, 2018). "Although there are no published studies regarding the role of WNT10B in CCA, studies from other cancers suggest that WNT10B overexpression promotes carcinogenesis." (PMID 23110045, 2012). "Among WNT family genes, WNT10B is expressed in carcinoma cells and adipocytes and is known to inhibit adipogenesis." (PMID 22927882, 2012).